LPAR3 (lysophosphatidic acid receptor 3)
Diseases named in the same sentence as LPAR3 in open-access papers (continued):
Sharing a sentence is not in itself a finding about the gene and the disease.
osteosarcoma (3 papers, 2021 to 2023). A usually aggressive malignant bone-forming mesenchymal neoplasm, predominantly affecting adolescents and young adults. "Importantly, the AP003352.1/miR-141-3p/LPAR3 axis can better serve as a multi-gene diagnostic marker for osteosarcoma." (PMID 37727685, 2023). "Herein, our study demonstrated that the AP003352.1/miR-141-3p axis drives LPAR3 expression to induce the malignant progression of osteosarcoma." (PMID 37727685, 2023). "We demonstrated a notably high expression of LPAR1 and its essential role in osteosarcoma cell invasion and metastasis, whereas the expression of LPAR3 was relatively high in some osteosarcoma cell lines." (PMID 34302117, 2021). "Further study is needed; however, LPAR3 might also play some roles in the invasion of osteosarcoma cells expressing low levels of LPAR1." (PMID 34302117, 2021). "However, the regulatory mechanism of the ceRNA network through which LPAR3 participates in osteosarcoma has not been clarified." (PMID 37727685, 2023).
triple-negative breast carcinoma (3 papers, 2015 to 2023). An invasive breast carcinoma which is negative for expression of estrogen receptor (ER), progesterone receptor (PR), and human epidermal growth factor receptor 2 (HER2). "LPAR1 and LPAR6 gene expression were highest in ER+HER2– (estrogen-receptor-positive, human-epidermal-growth-factor-receptor-negative) tumors and lowest in TNBC (triple negative breast cancer) tumors in all three cohorts, while this pattern was reversed for LPAR2 and LPAR3 (all p < 0.001)." (PMID 37372960, 2023).
atherosclerosis (2 papers, 2015 to 2016). A disease characterized by the build-up of fatty material and calcium deposition in the arterial wall resulting in partial or complete occlusion of the arterial lumen. "CXCL1 is also involved in atherosclerosis, and LPAR3 is required for monocyte recruitment to atherosclerotic lesions by oxidized LDL." (PMID 25965835, 2015).
breast tumor (2 papers, 2015 to 2018). "Variances between different breast tumor types are also likely as e.g. also LPAR3 levels can differ significantly." (PMID 30567518, 2018). "Depending on the breast tumor subtype, elevated LPAR3 mRNA levels have been reported." (PMID 30567518, 2018).
esophageal squamous cell carcinoma (2 papers, 2021 to 2022). Esophageal squamous cell carcinoma (ESCC) is a type of esophageal carcinoma (EC) that can affect any part of the esophagus, but is usually located in the upper or middle third. "In esophageal squamous cell carcinoma, circular RNA LPAR3 (circLPAR3) was found to be severely overexpressed both in vitro and in vivo promoting ESCC cell migration, invasion, and metastasis." (PMID 34162394, 2021). "For example, studies have shown that microRNA LPAR3 can upregulate MET gene expression and activate the PI3K/Akt pathway, promoting the migration, invasion and metastasis of esophageal squamous cell carcinoma (ESCC) cells in vivo and in vitro." (PMID 36502446, 2022).
Hutchinson-Gilford progeria syndrome (2 papers, 2022 to 2024). "Our prior study revealed that lysophosphatidic acid receptor 3 (LPA3) mitigates oxidative stress and cellular senescence in Hutchinson-Gilford progeria syndrome (HGPS)." (PMID 38397002, 2024).
preeclampsia (2 papers, 2014 to 2020). Preeclampsia is a hypertensive disorder of pregnancy that is characterized by new-onset hypertension with proteinuria presenting after 20 weeks of gestation, and depending on mild or severe forms may initially present with severe headache, visual disturbances, and hyperreflexia. "They found that dysregulation of LPA signalling as mediated by LPA specific G-protein-coupled receptors (LPAR), and more specifically LPAR3, may be associated with placental dysfunction in preeclampsia." (PMID 33370367, 2020).
renal fibrosis (2 papers, 2019 to 2022). A final common manifestation of a wide variety of chronic kidney diseases characterized by glomerulosclerosis and tubulointerstitial fibrosis. "In the same model, LPAR1, LPAR3, and ATX-expression levels are upregulated upon disease; administration of the LPAR1/LPAR3 antagonist BMS002 ameliorates glomerular filtration and renal fibrosis, while it reduces macrophage infiltration and podocyte loss." (PMID 35806457, 2022). "All of these studies suggest that the LPA–LPAR axis regulates renal fibrosis differently for different kidney cell types or different tissues, and that at least two receptors, LPAR1 and LPAR3, might be important contributors to renal fibrosis." (PMID 31212704, 2019).
acute liver failure (1 paper, 2023). Rapid deterioration of liver function causing encephalopathy and coagulopathy. "Recently, the ATX-LPA axis was demonstrated to modulate the innate immune response in patients with acute liver failure via lysophosphatidic acid receptor 1 (LPAR1) and lysophosphatidic acid receptor 3 (LPAR3)." (PMID 37528089, 2023).
astrocytomas (1 paper, 2021). "Therefore, we constructed Kaplan–Meier graphs using TCGA data for astrocytoma grades II, III and IV with low and high expression of LPAR1, LPAR3 and ENPP2." (PMID 33916643, 2021).
COVID-19 (1 paper, 2024). A disease caused by infection with severe acute respiratory syndrome coronavirus 2. "Furthermore, we modeled the LPAR1, LPAR3, and LPAR6 in a complex with the COVID-19 spike protein and performed a docking study of selected drugs with the LPAR-Spike complex." (PMID 38383841, 2024).
epilepsy (1 paper, 2021). A brain disorder characterized by episodes of abnormally increased neuronal discharge resulting in transient episodes of sensory or motor neurological dysfunction, or psychic dysfunction. "Higher expression levels were observed for ADPRC, calreticulin, LPAR3 and transgelin 3 across the 3 rat models of epilepsy." (PMID 33859251, 2021). "This study introduces involvement of ADPRC and LPAR3 in epilepsy so that inhibition of these components significantly suppressed seizure and epileptiform activity in full kindled rats and hippocampal slice, respectively." (PMID 33859251, 2021). "Therefore, changes in ADPRC and LPAR3 proteins across the 3 rat models of epilepsy were probed by Western blot analysis and validated using immunohistochemistry." (PMID 33859251, 2021). "The role played by ADPRC and LPAR3 components of Ca2+ influx pathways in epilepsy has not yet been demonstrated." (PMID 33859251, 2021). "In the treatment of epilepsy, the role played by ADP-ribosylcyclase (ADPRC) and lysophosphatidic acid receptor 3 (LPAR3) as components of Ca2+ influx pathways has yet not been demonstrated." (PMID 33859251, 2021).
glomerulosclerosis (1 paper, 2022). A hardening of the kidney glomerulus caused by scarring of the blood vessels. "Simultaneously, another inhibitor of LPAR1/LPAR3 ameliorates albuminuria and glomerulosclerosis, the main pathological feature of type 2 DN." (PMID 35806457, 2022).
Insulin resistance (1 paper, 2023). Increased resistance towards insulin, that is, diminished effectiveness of insulin in reducing blood glucose levels. "In PCOS animals exhibiting insulin resistance, BBR improves endometrial receptivity via modulating the endometrial implantation genes (LPAR3, αvβ3, and HOXA11), although the exact mechanism is still under investigation." (PMID 36676074, 2023).
ischemic stroke (1 paper, 2021). A stroke disorder caused by obstruction of blood flow to the brain, due to thrombotic (local blood clot formation) or embolic (due to a blood clot or other material traveling from another site) event. "Regulatory axis, such as SND1-IT1/NAPA-AS1/LINC01001-miR-24-3p-LPAR3/ADORA1 and LUCAT1/ASAP1-IT2-miR-93-3p-GPR17 may play important roles in the progression of ischemic stroke." (PMID 34483854, 2021). "In this study, the expression of LPAR3 increased in patients with ischemic stroke, but there has been no prior report on the relationship between LPAR3 and ischemic stroke." (PMID 34483854, 2021). "lncRNA-miRNA-mRNA regulatory axis such as SND1-IT1/NAPA-AS1/LINC01001-miR-24-3p-LPAR3/ADORA1 and LUCAT1/ASAP1-IT2-miR-93-3p-GPR17 may play important roles in the progression of ischemic stroke." (PMID 34483854, 2021). "Thus, we speculated that KCNQ1OT1, SND1-IT1, NAPA-AS1, and LINC01001 may interact with miR-24-3p and facilitate the regulation of LPAR3 and ADORA1 in ischemic stroke." (PMID 34483854, 2021). "In conclusion, LPAR3, ADORA1, GPR17, and OPRM1 may serve as therapeutic targets of ischemic stroke." (PMID 34483854, 2021). "LPAR3, ADORA1, GPR17, and OPRM1 may serve as therapeutic targets of ischemic stroke." (PMID 34483854, 2021).
liver fibrosis (1 paper, 2022). "So, LPAR1/LPAR3 down-regulation could provide therapeutic benefits against hepatic fibrosis." (PMID 35648193, 2022). "Moreover, SML protected against liver fibrosis in a dose-dependent manner as indicated by down-regulation of LPAR1, LPAR3, CTGF, TGF-β1/Smad3, and α-SMA expressions and a decrease in pSmad3 level, as well as an up-regulation of Smad7 expression." (PMID 35648193, 2022).
mastitis (1 paper, 2023). Inflammation of breast tissue during lactation or postpartum due to an obstructed duct or infection. "In the MGI database, we found one gene disruption (Mfge8) and five transgenic mouse models for Lao1, Enpp2, Lpar1, Lpar2, and Lpar3 that resulted in abnormal mammary gland physiology and were also associated with mastitis." (PMID 36759924, 2023). "Bovine orthologs of the Mfge8 and Lpar3 associated with mastitis phenotypes in knockout and transgenic mouse models were also reported differentially expressed during mammary infection in cattle." (PMID 36759924, 2023).
Miscarriage (1 paper, 2022). A pregnancy that ends at a stage in which the fetus is incapable of surviving on its own, defined as the spontaneous loss of a fetus before the 22th week of pregnancy. "High levels of lysophosphatidic acid receptor 3 (LPAR3) and integrin αvβ3 led to reduced endometrial receptivity and subsequent miscarriage." (PMID 36699064, 2022).
multiple myeloma (1 paper, 2018). "For example, during the progression of multiple myeloma, LPAR1 and LPAR3 transduce opposite signals to determine MSC fates as either myeloma supportive or suppressive stroma." (PMID 29898789, 2018).
oral carcinoma (1 paper, 2014). "The results demonstrate LPA-stimulated migration in oral carcinoma cells through LPAR3, mediated further by PKC, which acts either in concert with or independently of EGFR transactivation." (PMID 24928086, 2014). "LPAR3, which was found to be the most likely mediator of the migratory effect of LPA in the oral cancer cells studied here, is known to couple to Gq and phospholipase C β (PLC-β) and can thus convey activation of PKC." (PMID 24928086, 2014). "Taken together, these results suggest an involvement of LPAR3 in LPA-stimulated migration in E10 and SCC-9 oral carcinoma cells." (PMID 24928086, 2014). "While studies in various cancers indicate that different receptors may be involved in LPA-regulated cell migration, our present results strongly suggest that in the two oral cancer cell lines where LPA stimulated the migration, E10 and SCC-9, the effect was mediated by LPAR3." (PMID 24928086, 2014).
Sepsis (1 paper, 2022). Sepsis is defined as life-threatening organ dysfunction caused by a dysregulated host response to infection. "Together, these results showed that excessive NETs generation in Lpar3-/- sepsis mice may be the main cause of their aggravated sepsis injury." (PMID 35464399, 2022). "The mortality rate and degree of lung damage in Lpar3-/- mice with sepsis were significantly reduced after the destruction of NETs by DNaseI treatment." (PMID 35464399, 2022). "To elucidate the changes in the molecular mechanisms of monocytes in Lpar3-/- mice with sepsis, we examined the related signaling pathway proteins." (PMID 35464399, 2022). "The results revealed that monocyte MyD88 protein and p-P65 NFκB protein expression were significantly increased in Lpar3-/- mice with sepsis." (PMID 35464399, 2022). "DNaseI-treated Lpar3-/- mice with sepsis exhibited significantly higher survival rates than the PBS-treated Lpar3-/- mice with sepsis." (PMID 35464399, 2022). "Blood coagulation measurements demonstrated that, compared with that in WT mice with sepsis, Lpar3-/- mice with sepsis had significantly longer plasma prothrombin time (PT), less fibrinogen levels (FIB), and more D-dimer content." (PMID 35464399, 2022). "Plasma from Lpar3-/- mice with sepsis was found to have an enhanced ability to induce NETs compared to that from the WT controls, which suggests that the plasma of Lpar3-/- mice with sepsis contain more NETs inducers." (PMID 35464399, 2022). "The results showed that the plasma of Lpar3-/- mice with sepsis had an enhanced ability to induce NETs compared to that of the WT controls." (PMID 35464399, 2022). "When mice were administered 7 mg/kg LPS, all Lpar3-/- mice with sepsis died within 32 hours, with a survival rate of 0%." (PMID 35464399, 2022). "The plasma of Lpar3-/- mice with sepsis is more capable of inducing NETs, suggesting the presence of more inducers." (PMID 35464399, 2022). "To confirm that LPA3 affects the production of NETs during sepsis, we isolated plasma from WT and Lpar3-/- mice with sepsis, co-cultured with isolated WT neutrophils separately." (PMID 35464399, 2022). "qRT-PCR and western blotting revealed that CD14 expression was significantly increased in monocytes from Lpar3-/- mice with sepsis." (PMID 35464399, 2022). "Hematoxylin and eosin (H&E) staining showed significant hyperplasia of the splenic red marrow in Lpar3-/- mice with sepsis, suggesting that LPA3 deficiency caused a more intense inflammatory response in sepsis." (PMID 35464399, 2022). "In addition to the spleen, H&E staining revealed increased levels of lung injury in Lpar3-/- mice with sepsis, and microthrombi were present in the small vessels of the lungs of Lpar3-/- mice with sepsis." (PMID 35464399, 2022). "In addition, we observed that Lpar3-/- mice with sepsis had almost no epidermal blood flow, and microcirculatory perfusion was seriously blocked." (PMID 35464399, 2022). "Furthermore, in vitro experiments with co-cultured monocytes and neutrophils demonstrated that monocytes from Lpar3-/- mice promoted the formation of NETs, suggesting that LPA3 acting on monocytes inhibits the formation of NETs and plays a protective role in sepsis." (PMID 35464399, 2022). "Although LPA has been functionally identified to induce NETs, whether and how LPA receptors, especially lysophosphatidic acid receptor 3 (LPA3), play a role in the development of sepsis has never been explored." (PMID 35464399, 2022).
Trachea Adenoid Cystic Carcinoma (1 paper, 2021). "Furthermore, LPAR3 is associated with Tracheal cancer and Trachea Adenoid Cystic Carcinoma." (PMID 34884814, 2021).
tumor (35 papers, 2004 to 2025). "Moreover, LPAR3 downregulation might be associated with tumor progression concomitant with autophagy induction in Ras-transformed cells." (PMID 36088312, 2022). "While functional analysis did not result in identification of any enriched terms or pathways, increased expression of genes associated with tumor progression, aggressiveness, and survival was observed in CCA compared to HCC components, including LPAR3." (PMID 40424447, 2025). "Genes implicated in cell proliferation and migration such as Tgfβ3, Fzd2, Fzd9, and Lpar3 showed marked downregulation in tumor tissues post-FAA treatment." (PMID 38613073, 2024). "Recent reports have demonstrated that LPAR3 regulates either positively or negatively cancer cell progression depending on tumor cell type, implying a more complicated role for LPAR3." (PMID 36088312, 2022). "Consistent with our results, several studies have suggested that LPAR3 is epigenetically silenced in tumor cells through the hypermethylation of its promoter." (PMID 36088312, 2022). "Paradoxical downregulation of LPAR3 exerts cooperative tumor-promoting activity with MEK activation through autophagy induction in Ras-transformed cells." (PMID 36088312, 2022). "To better understand the biological significance of LPAR3 in tumor cells, we are investigating the changes in LPAR3 expression and autophagic flux during cellular transformation using an in vitro two-stage CTA model system." (PMID 36088312, 2022). "Our results suggest that the downregulation of LPAR3 exerts cooperative tumor-promoting activity with MEK activation through autophagy induction in Ras-transformed cells." (PMID 36088312, 2022). "With both tumor cells and TAM expressing similar levels of LPAR1 and LPAR2, LPAR3 was predominantly expressed in tumor cells, while LPAR5 and LPAR6 were selective for TAM." (PMID 32397679, 2020). "LPA in ascites apparently targets tumor cells and TAMs via specific receptors, since LPAR1 and LPAR2 are expressed at similar levels by both cell types, LPAR3 is selective for tumor cells, LPAR5 and LPAR6 for TAMs." (PMID 27215396, 2016). "Significant overexpression of LPAR3 has been identified in HCC tumor margins and was interestingly overexpressed in the CCA portion of combined HCC-CCA, potentially owing to the increased aggressiveness along with NEFL and TUSC7 that were also overexpressed in the CCA portions." (PMID 40424447, 2025). "LPAR3, which is overexpressed in ovarian tumours, promotes Gi/MAPKs/nuclear factor kappa-light-chain-enhancer of activated B cells (NF-κβ) signalling to drive tumour growth and metastasis." (PMID 38607068, 2024). "In this study, the downregulation of LPAR3 during cellular transformation suggests that LPAR3 might act as a tumor suppressor in tumorigenesis." (PMID 36088312, 2022). "However, our findings also indicate that downregulation of LPAR3 due to promoter methylation enhances tumor progression by increasing autophagic flux in Ras-transformed cells." (PMID 36088312, 2022). "Furthermore, Ki16425 is one of the most investigated agents targeting both LPAR1 and LPAR3, and its anti-tumor effects were validated in several cancer cells." (PMID 34209775, 2021). "Resistance to cisplatin in this tumour type is also potentiated by hypoxia, which increases the expression of both LPAR2 and LPAR3." (PMID 38607068, 2024). "On the other hand, the rest of the LPARs (LPAR1, LPAR3 and LPAR5) presumably are involved in the tumor growth via modulating its microenvironment." (PMID 31652837, 2019). "In tumor cells, LPAR1, LPAR2, and LPAR3 are the major subtypes, while LPAR5 and LPAR6 are expressed only at very low levels in a subset of patients, if at all." (PMID 30353652, 2019). "In line with this, elevated LPAR1/LPAR3 expression in HCC was evidenced in the microenvironment between the tumor and non-tumor liver (NTL) and LPAR3 expression coincided with cancer stem cell markers expression." (PMID 31652837, 2019).